MTOR (mechanistic target of rapamycin kinase)
Diseases named in the same sentence as MTOR in open-access papers (continued):
Sharing a sentence is not in itself a finding about the gene and the disease.
endometriosis (continued). "In recent years, the investigation of mTOR signaling in endometriosis is still evolving." (PMID 35408777, 2022). "Interestingly, these findings were observed mainly in women with a minimal-mild stage of the disease, suggesting that the PI3K/AKT/mTOR pathway plays a critical role in the onset of endometriosis." (PMID 35408777, 2022). "From this review, it follows that mTOR and eIF signaling are deranged in adenomyosis, endometriosis, endometritis, and typical endometrial hyperplasia and may serve as druggable targets in these life-impacting diseases." (PMID 35408777, 2022). "And the results of KEGG analysis also identified that the effect of kaempferol on endometriosis may be related to PI3K/AKT/mTOR pathway." (PMID 36184634, 2022). "Moreover, LY294002 (a PI3K/AKT/mTOR signaling pathway inhibitor) treatment also inhibited the malignant phenotype of endometriosis." (PMID 34055578, 2021). "PI3K/AKT/mTOR signaling pathway was activated in women with endometriosis and may modulate the survival and proliferation of endometriotic cells." (PMID 34055578, 2021). "Nowadays, targeting the mTOR axis with the existing drugs is not acceptable for endometriosis management, given its ubiquitous role and the associated side effects." (PMID 34064854, 2021). "Taken together, miR-342 targets ANXA2 to activate the PI3K/AKT/mTOR signaling pathway, thereby promoting the malignant-like phenotype of endometrial stromal cells, highlighting miR-342 inhibition as a promising approach for the treatment of endometriosis." (PMID 34055578, 2021). "Furthermore, overexpression of ‘PI3K-Akt-mTOR’ has been noted in endometriosis and certain types of cancers (ovarian, breast and urothelial), and therapeutic agents targeting its core components have been developed." (PMID 32121467, 2020). "MAPK and ‘PI3K-Akt-mTOR’ are expressed differently, however, there is evidence that both are activated by steroid hormones and growth factors, supporting a role for sex hormones in the pathogenesis of endometriosis and migraine." (PMID 32121467, 2020). "The PI3K-Akt-mTOR pathway is one of the major signaling pathways in endometriosis." (PMID 32210799, 2020). "In addition, an important finding of the present study was that EPHA3 was poorly expressed, while the mTOR signaling pathway was activated in the endometrial tissues in mouse models with endometriosis." (PMID 31262977, 2019). "Finally, preclinical evidence suggests the possibility of applying mTOR modulators to ameliorate fertility issues associated with POF, PCOS, and endometriosis." (PMID 31649622, 2019). "Moreover, the inhibition of mTOR can suppress endometriotic foci in a rat/mouse model of endometriosis and promote human endometriotic cell apoptosis via autophagy induction." (PMID 31649622, 2019). "In conclusion, the evidence collected from our study supports the contribution of the EPHA3 in the treatment of patients with endometriosis by means of its promoting effects on macrophage autophagy and apoptosis through inactivation of the mTOR signaling pathway." (PMID 31262977, 2019). "On comparing with those of the normal group, it was observed that the mRNA and protein levels of EPHA3 in the endometrial tissues of mice in the endometriosis group significantly decreased, while the mRNA and protein levels of mTOR and the ratio of p-mTOR/mTOR increased (both P<0.05)." (PMID 31262977, 2019). "The aim of the present study is to assess the potential effects of erythropoietin-producing hepatocellular carcinoma A3 (EPHA3) on endometriosis, with emphasis on the autophagy and apoptosis of macrophages via inhibition of the mammalian target of rapamycin (mTOR) signaling pathway." (PMID 31262977, 2019). "mTOR has been reported to be phosphorylated and activated in endometriosis and OCCC specimens." (PMID 26497956, 2015). "Furthermore, the PI3K/mTOR/AKT pathway is activated in endometriosis, and inhibition of this pathway represents a potential therapeutic modality." (PMID 26779118, 2015).
endometriosis (continued). "In endometriosis, hyperestrogenic conditions and chronic inflammation cause sustained mTOR activation, NF-κB positive feedback, and constitutive stimulation of the PI3K/AKT/mTOR and MAPK/ERK pathways, resulting in autophagy suppression, abnormal proliferation, lesion maintenance, and infertility." (PMID 41009686, 2025). "In summary, inhibitors of the PI3K/Akt/mTOR pathway may be potential treatments for endometriosis." (PMID 39579091, 2024). "Additionally, mTOR inhibitors have shown efficacy as monotherapies for endometriosis." (PMID 39579091, 2024). "Thus, although it is unclear whether mTOR inhibitors can prevent carcinogenesis, activation of the PI3K/mTOR pathway is likely involved in the malignant transformation of endometriosis." (PMID 39579091, 2024). "Additionally, it has been reported that part of the effect of hormonal agents on endometriosis may be mediated through the autophagy effect of mTOR inhibition." (PMID 39579091, 2024). "Autophagy may be dynamically regulated through various intrinsic (e.g., PI3K/AKT/mTOR signal transduction network) and extrinsic (e.g., hypoxia and iron‐mediated oxidative stress) pathways, contributing to the development and progression of endometriosis." (PMID 38645639, 2024). "Hypoxia, inflammation, and the immune microenvironment further regulate this pathway and may be essential for endometriosis-related cancer transformation, potentially positioning the mTOR pathway at the centre of multiple molecular pathways leading to cancer development." (PMID 38893278, 2024). "Moreover, endometriosis is frequently accompanied by resistance to progesterone, a condition that may also be associated with PI3K/AKT/mTOR pathway activation, as the latter seems to modulate the response of ectopic endometrium to progesterone." (PMID 37627318, 2023). "More recently, PI3K/AKT/mTOR signaling pathway targeted by the miR-199a-5p/ZEB1 axis could inhibit the epithelial-mesenchymal transition of ovarian ectopic endometrial stromal cells during endometriosis." (PMID 34055578, 2021). "Moreover, we assess whether strategies to improve or suppress mTOR expression could have therapeutic potential for reproductive diseases like premature ovarian failure, polycystic ovarian syndrome, and endometriosis." (PMID 31649622, 2019). "Lipoprotein A4 suppresses inflammation and enhances autophagy via the AhR/mTOR/AKT pathway, thereby inhibiting endometriosis." (PMID 40144566, 2025). "Growing evidence implicates these miRNAs in key endometriosis-related pathways, such as IKKβ/NF-κB, PI3K/Akt/mTOR, and MAPK (ERK1/2, p38, and JNK)." (PMID 40429709, 2025). "LncRNA IGF2-AS facilitates the progression of endometriosis by targeting the miR-370-3p/IGF2 axis and activating the PI3K/AKT/mTOR signaling pathway." (PMID 40144566, 2025). "Our data revealed significantly higher intracellular mTOR and AKT expression in TAMs (CD14+) and epithelial cells from endometriosis patients compared to HGS-OC." (PMID 40723209, 2025). "In endometriosis, PPI inhibits growth and migration of endometrial stroma cells by inducing autophagy through Akt/mTOR signaling." (PMID 38745316, 2024). "A recent transcriptome meta-analysis comparing the eutopic endometrium of women with stage III–IV endometriosis to normal endometrium from healthy counterparts demonstrated the enrichment of the PI3K, AKT, mTOR, and TGF signalling pathways." (PMID 38893278, 2024). "Several recent reviews have examined the relationship between endometriosis and the PI3K/Akt/mTOR pathway." (PMID 39579091, 2024). "Therefore, dienogest might block mTOR signaling pathway and mitigate endometriosis." (PMID 39324359, 2024). "A meta-analysis of transcriptome microarrays reported that PI3K/mTOR pathway activation, transforming growth factor-β signalling, and interferon α/γ response are abundant only in stage III–IV endometriosis." (PMID 39579091, 2024).
endometriosis (continued). "Genes involved in the initiation and regulation of autophagy (e.g., mTOR, CXCR4, and ESR1) are upregulated in endometriosis." (PMID 38645639, 2024). "Synchronous alterations in mTOR signaling and ARID1A expression are highly frequent in EAOCs and their precursor endometriosis lesions, reinforcing the idea that both genetic events promote EAOC development in a synergistic manner." (PMID 37627318, 2023). "Although few studies have been conducted on PI3K/AKT in endometriosis, in one of the previous studies, phosphorylated AKT was observed in postmenopausal women with ovarian endometriosis, and phosphorylated mTOR was increased in ectopic lesions." (PMID 35052675, 2022). "The identification of AKT1, or more generally, genes in the PI3K/AKT/mTOR pathway (including MTOR, PIK3CA, and PIK3R1 in addition to ATK1), is in line with current interests targeting this pathway in endometriosis." (PMID 35401535, 2022). "In this study, a PI3K/mTOR dual inhibitor, GSK2126458, was tested in a mouse model of induced endometriosis and proven to be effective in inhibition of lesion growth, chronic inflammation and pain related behaviors." (PMID 35052864, 2022). "The upregulated gene ATP6V1A was involved in ‘mTOR signaling’, an enriched KEGG pathway known to contribute to the development of endometriosis." (PMID 33901012, 2021). "miR-106a-5p targets FOXC1 to exert an inhibitory effect on endometriosis (EMS) development, likely through the PI3K/Akt/mTOR signaling pathway." (PMID 34365889, 2021). "PI3K AKT mTOR, TGF signalling, and interferon alpha/gamma responses were enriched exclusively in stage III-IV endometriosis." (PMID 31941945, 2020). "Distinct pathways that existed between stage I-II and stage III-IV endometriosis included: adipogenesis, PI3K AKT mTOR signalling, peroxisome, glycolysis, TGF beta signalling, heme metabolism, and interferon gamma response." (PMID 31941945, 2020). "After successful modeling, the uterine tissues of endometriosis mice presented with a low expression of EPHA3 and activated mTOR signaling pathway." (PMID 31262977, 2019). "We obtained 45 potential pathways from the KEGG (Kyoto Encyclopedia of Genes and Genomes) database and particularly mTOR and VEGF signaling pathway caught our attention due to its close potential relation to pathogenesis of endometriosis (resp)." (PMID 26366419, 2015). "This review summarizes current findings on the molecular mechanisms driving metabolic reprogramming in endometriosis, including the roles of mitochondrial dysfunction, hypoxia-inducible factor (HIF) signaling, the PI3K/AKT/mTOR pathway, inflammatory cytokines, and genetic and epigenetic regulators." (PMID 40573210, 2025). "Conversely, endometriosis showed a dominant M2 profile (CD14+/CD163+), elevated intracellular mTOR and AKT expression in both TAMs and epithelial cells (p < 0.01), and significantly higher ascitic ROS and free iron levels (p = 0.047 and p < 0.0001, respectively)." (PMID 40723209, 2025). "Regarding the intracellular markers of the metabolic mTOR pathway, we found that the intracellular levels of mTOR and AKT in macrophages (CD14+) isolated from the ascitic fluid were significantly higher in endometriosis than in papillary serous ovarian cancer (p = 0.001 and p = 0.002, respectively)." (PMID 40723209, 2025). "Elevated expression of the mTOR activators AXL and SHC1 has been observed in endometriosis." (PMID 39579091, 2024). "Mechanistically, the mTOR inhibition acts as a hub to activate autophagy mechanisms through increased expression of Beclin1, LC3II, Bnip3, Ambra1, and Parkin in a rat model of endometriosis." (PMID 38645639, 2024). "As of 2024, there have been no reports of PI3K/Akt/mTOR pathway inhibitors being approved or tested in clinical trials, specifically for endometriosis." (PMID 39579091, 2024).
endometriosis (continued). "Since mTOR pathway alterations seem to occur as an early event in the onset of endometriosis, it would not be surprising that continuous misfunction of this proliferation-inducing signaling can increase the malignant potential of endometriotic cells." (PMID 37627318, 2023). "The protein kinase mTOR regulates the process of cell growth, proliferation and movement, as well as translation and transcription processes, while VEGF factor intensifies the process of angiogenesis in endometriosis." (PMID 34638893, 2021). "Genes having Pgene < 0.1 for both endometriosis and migraine (Pbinomial-test = 1.85 ×10−°3) were significantly enriched for biological pathways, including interleukin-1 receptor binding, focal adhesion-PI3K-Akt-mTOR-signaling, MAPK and TNF-α signalling." (PMID 32121467, 2020). "The mTOR (mammalian target of rapamycin kinase) kinase controls the processes of growth, proliferation, and mobility of cells, as well as translation and transcription processes, while VEGF enhances the process of angiogenesis in endometriosis." (PMID 33153202, 2020). "Furthermore, the activation of mTOR signalling upregulates the expression of WD repeat domain protein 5, which interacts with the TET2 protein to induce the overexpression of oestrogen receptors, promoting the development of endometriosis." (PMID 39579091, 2024). "However, the effects of mTOR inhibitors as immunosuppressants on endometriosis have not been thoroughly reported, even in preclinical studies, and further research is required." (PMID 39579091, 2024). "Transcriptome and protein expression analyses indicated higher levels of genes involved in PI3K/AKT/mTOR signaling in endometriotic lesions than in normal endometria, especially for patients at advanced stages (stage III to IV) or patients with postmenopausal endometriosis." (PMID 35052864, 2022). "Additionally, it has been demonstrated by in vivo experiments that during endometriosis, the inhibition of autophagy by increasing extracellular signal-regulated kinase (ERK), mammalian target of rapamycin (mTOR) and serine/threonine kinase (AKT)/mTOR activity further downregulates apoptosis." (PMID 34064854, 2021). "Overexpression of EPHA3 inhibited the activation of the mTOR signaling pathway, down-regulated bcl-2 expression, up-regulated the expression of Atg3, LC3-II/LC3-I, Beclin1, bax and fas, and also promoted the autophagy and apoptosis of macrophages in endometriosis mice." (PMID 31262977, 2019). "Additionally, in the current study, a negative correlation was evident between the mTOR signaling pathway and EPHA3, with emphasis on the role as a mediator in the pathogenesis of endometriosis." (PMID 31262977, 2019).
kidney cancer (64 papers, 2010 to 2025). Primary or metastatic malignant neoplasm involving the kidney. "Regarding specific pathways, the eigenvector centrality score revealed some of the main pathways associated with the pathogenesis of kidney cancer, such as mTOR, ascorbate and aldarate metabolism, unsaturated fatty acids, and mismatch repair." (PMID 40740488, 2025). "The mTOR gene is another classic mutation target seen in kidney cancer and is a key focal point for emerging treatment strategies in ccRCC, combining mTOR pathway inhibitors with an immune checkpoint blockade." (PMID 39457484, 2024). "Increased mTOR signaling activity has been associated with prostate, brain, lung, bladder, and kidney cancers." (PMID 37893061, 2023). "The significance of the phosphoinositide 3-kinase (PI3K)/protein kinase B (AKT)/mechanistic target of rapamycin (mTOR) pathway associated with the escape from apoptosis, growth, and proliferation of cells in kidney cancer must be noted." (PMID 31110513, 2019). "Ochratoxin A has been shown to increase and decrease methylation in various genes associated with the mammalian target of the rapamycin (mTOR) signalling pathway in rat kidney, which may play a role in the development of kidney cancer." (PMID 40700165, 2025). "The promising results obtained in this patient suggest that combined bevacizumab plus erlotinib may offer a valid treatment option for advanced HLRCC-associated kidney cancer, even after failures of mTOR inhibitor and/or VEGFR TKI based therapies." (PMID 31182090, 2019). "In pre-kidney cancer studies, the mTOR inhibitors everolimus and tesilimus have been approved by the FDA for treating advanced metastatic renal cell carcinoma." (PMID 38730456, 2024). "Among the five signaling pathways obtained, the mTOR signaling pathway is frequently activated, and regulation of mTOR activity is frequently lost in various human cancers, such as breast, prostate, lung, liver, and kidney cancers." (PMID 38600527, 2024). "Drugs targeting mTOR pathways, such as lenvatinib, everolimus, and sirolimus, have gained regulatory approval for treating kidney cancer." (PMID 39457484, 2024). "In patients with kidney cancer, the three types of drugs that accounted for 100% of the expenditure included tyrosine kinase inhibitors (65.65%), immunotherapy (26.24%), and the mTOR inhibitor temsirolimus (8.11%)." (PMID 37754495, 2023). "As is known, the PI3K/AKT/mTOR signaling pathway is often activated in kidney cancer and leads to increased cell growth, proliferation, and metastasis." (PMID 37443682, 2023). "Pathways such as VEGF, EGF and mTOR are known to be one of the major mechanisms of tumorigenesis including kidney cancer." (PMID 36286049, 2022). "A new method for mRNA profiling of ribosome load defines the pan-genomic interplay of transcriptional and translational regulation mediated by environment-sensing HIF and mTOR pathways in kidney cancer cells, offering insights into rational therapy." (PMID 36097292, 2022). "Its application to kidney cancer cells reveals extensive translational reprogramming by mTOR, strongly affecting many metabolic enzymes and pathways." (PMID 36097292, 2022). "Even the mTOR signaling pathway has a relevant role in the development of kidney cancer and it represents an attractive therapeutic target among several subgroups of RCC." (PMID 34207825, 2021). "Studies have also confirmed that the mammalian target of rapamycin (mTOR) pathway is related to the genesis and progression of kidney cancer, which paves the way for new drugs for ccRCC." (PMID 34667158, 2021). "PI3K/AKT/mTOR pathway plays a pivotal role in cancer pathogenesis and progression, and mTOR is frequently activated in various malignancies, such as breast, prostate, lung, liver, and kidney cancers (Posadas, Limvorasak & Figlin, 2017)." (PMID 34458019, 2021).